PAOX (polyamine oxidase)
Description:
Flavoenzyme which catalyzes the oxidation of N(1)- acetylspermine to spermidine and is thus involved in the polyamine back-conversion. Can also oxidize N(1)- acetylspermidine to putrescine. Substrate specificity: N(1)- acetylspermine = N(1)-acetylspermidine > N(1),N(12)-diacylspermine >> spermine. Does not oxidize spermidine. Plays an important role in the regulation of polyamine intracellular concentration and has the potential to act as a determinant of cellular sensitivity to the antitumor polyamine analogs.
Synonyms: PAO
Tractability: Small molecule: it belongs to a druggable protein family. PROTAC: a small molecule that binds it is known.
Target class: Enzyme; Oxidoreductase
Gene: Protein-coding gene on chromosome 10 (133,379,246 to 133,392,078, forward strand). Ensembl gene ENSG00000148832.
Subcellular location: Peroxisome; Cytoplasm
Subcellular location (Human Protein Atlas): Centrosome; Nucleoplasm
Pathways (Reactome):
Metabolism: Interconversion of polyamines; PAOs oxidise polyamines to amines
Protein localization: Peroxisomal protein import
Gene Ontology:
Molecular function: N(1)-acetylpolyamine oxidase (3-acetamidopropanal-forming) activity; polyamine oxidase activity; oxidoreductase activity
Biological process: positive regulation of spermidine biosynthetic process; putrescine biosynthetic process; putrescine catabolic process; spermidine catabolic process; spermine catabolic process; intracellular polyamine homeostasis; polyamine catabolic process; spermine metabolic process
Cellular component: cytosol; peroxisomal matrix; cytoplasm; peroxisome
Genetic constraint (gnomAD): Loss-of-function variants: 37 observed, 37.68 expected, observed/expected ratio (o/e) 0.98, 90% interval 0.75 to 1.29. The upper end of that interval is the gene's LOEUF score, 1.29, which puts it in group 5 of 6, group 1 being the genes least tolerant of losing a copy. Missense variants: 667 observed, 672.94 expected, observed/expected ratio (o/e) 0.99, 90% interval 0.93 to 1.06. Synonymous variants: 311 observed, 301.21 expected, observed/expected ratio (o/e) 1.03, 90% interval 0.94 to 1.13.
Homologues: Orthologues: chimpanzee PAOX (99% identical), macaque PAOX (97% identical), pig PAOX (83% identical), rat Paox (82% identical), guinea pig PAOX (82% identical), mouse Paox (81% identical), rabbit PAOX (70% identical), dog PAOX (61% identical), tropical clawed frog paox (54% identical), zebrafish PAOX (49% identical), Drosophila melanogaster CG8032 (34% identical), Drosophila melanogaster CG7460 (29% identical), and 6 more. Paralogues in human: SMOX (41% identical), KDM1A (20% identical), MAOB (19% identical), KDM1B (19% identical), IL4I1 (18% identical), MAOA (18% identical), PPOX (16% identical).
Diseases named in the same sentence as PAOX in open-access papers:
PAOX is named in the same sentence as 29 diseases in open-access papers, as found by Europe PMC text mining. Sharing a sentence is not in itself a finding about the gene and the disease. The quoted sentences say what the papers report.
breast carcinoma (3 papers, 2022 to 2023). "Previous studies have shown that high levels of acetylated polyamines are found in breast cancer in association with a simultaneous increase in spermidine and spermine N1 acetyltransferase (SAT1) activity and decreased polyamine oxidase activity." (PMID 37046602, 2023). "In this study, we found that among the genes involved in the polyamine pathway, polyamine oxidase (PAOX) mRNA levels were the most significantly reduced by treatment with 17β-estradiol in estrogen receptor (ESR)-positive MCF-7 breast cancer cells." (PMID 35886868, 2022). "Furthermore, we recently demonstrated that estrogen suppresses PAOX expression in an ESR2-dependent manner in MCF-7 breast cancer cells." (PMID 36142401, 2022).
glioblastoma (2 papers, 2015 to 2024). The most malignant astrocytic tumor (WHO grade IV). "Thus, in contrast to the cell lines used above, glioblastoma and neuroblastoma cell lines exhibit detectable PAOX activity." (PMID 38994986, 2024). "Indeed, all glioblastoma cell lines displayed a high level of resistance to doxorubicin, supporting the hypothesis that PAOX is a key regulator of the resistance of cells to genotoxic drugs." (PMID 38994986, 2024). "Therefore, PAOX might have a tumor suppressor activity and its deletion in many glioblastoma samples could provide a selective advantage to glioblastoma tumor cells." (PMID 25679508, 2015). "The final assessment of PAOX1’s possible role in resistance to doxorubicin was carried out in glioblastoma cells, as the GMB6138 cell line expressed high PAOX levels." (PMID 38994986, 2024). "Interestingly, among those genes we find the well-known glioblastoma oncogene EGFR and tumor suppressors CDKN2A and PTEN, but also novel candidates such as KRIT1 and PAOX described in the previous paragraph." (PMID 25679508, 2015).
autism (1 paper, 2016). Persistent deficits in social interaction and communication and interaction as well as a markedly restricted repertoire of activity and interest as well as repetitive patterns of behavior. "In addition, there is a report of a patient with autism, ID and microcephaly who showed duplication with a size of 170 Kb containing PAOX, MTG1 and SPRN genes." (PMID 28357200, 2016).
cervix adenocarcinoma (1 paper, 2024). "Next, we evaluated transcription of genes encoding PAOX and other polyamine-metabolizing proteins by RT-qPCR in several human cell lines, including Huh7.5 (hepatoma), A549 (lung adenocarcinoma), DU145 (prostate carcinoma), HeLa (cervix adenocarcinoma), and K562 (chronic myeloid leukemia)." (PMID 38994986, 2024).
chronic renal failure (1 paper, 2023). "Increased plasma polyamine oxidase activity and elevated acrolein levels have been reported in patients with chronic renal failure." (PMID 36979725, 2023).
clear cell renal cell carcinoma (1 paper, 2024). "Extremely low levels of PAOX mRNA were also previously reported for clear cell renal cell carcinoma." (PMID 38994986, 2024).
Hypertension (1 paper, 2019). The presence of chronic increased pressure in the systemic arterial system. "Consumption of foods containing excessive BA may cause symptoms such as migraines, sweating, nausea, hypotension, and hypertension, unless human intestinal amine oxidases—such as monoamine oxidase (MAO), diamine oxidase (DAO), and polyamine oxidase (PAO)—quickly metabolize and detoxify BA." (PMID 30769885, 2019).
lung carcinoma (1 paper, 2023). "This activity could be enhanced by inhibiting the PAOX enzyme, yielding a synergistic effect against lung cancer cells." (PMID 37759783, 2023).
neurodegenerative diseases of the eye (1 paper, 2018). "Our data suggest that inhibition of polyamine oxidase signaling can be considered as a therapeutic target to limit neuronal dysfunction in neurodegenerative diseases of the eye." (PMID 30686964, 2018).
oral cancer (1 paper, 2022). "Immunochemical staining proved that spermine oxidase, an effective polyamine oxidase, was upregulated in mouse oral cancer lesions." (PMID 36046649, 2022).
primary myelofibrosis (1 paper, 2024). Myelofibrosis with myeloid metaplasia is a myeloproliferative disease with annual incidence of approximately 1 case per 100,000 individuals and age at diagnosis around 60 (an increased prevalence is noted in Ashkenazi Jews). "Upregulation of PAOX was shown in the nucleus pulposus (NP) cells during the degeneration of intravertebral disks caused by IL-1β, as well as in patients with primary myelofibrosis." (PMID 38994986, 2024).
skin aging (1 paper, 2022). The gradual irreversible changes in structure of skin that occur as a result of the passage of time.. "Therefore, we propose that PAOX inhibition or downregulation could be a useful therapeutic strategy against skin aging due to inflammation or menopause." (PMID 36142401, 2022).
tumor (7 papers, 2015 to 2025). "Despite the detrimental effect of SSAT increase on tumor cells, the increase in polyamine acetylation can be reverted by the polyamine oxidase (PAOX) enzyme." (PMID 32256343, 2019). "In line, polyamine oxidase inhibitor delayed experimental tumor growth." (PMID 29670256, 2018). "The GSE54129 GC dataset and LASSO regression model (tumor vs. normal) were employed, and 6 significant differentially expressed genes (LAMP5, CEBPB, ARMC9, PAOX, VMP1, POC1A) were identified." (PMID 33052878, 2020). "Here, we show that PAOX transcription levels are extremely low in various tumor- and non-tumor cell lines and, in most cases, do not change in response to altered polyamine metabolism." (PMID 38994986, 2024). "Assessment of PAOX mRNA levels in several RNA-seq datasets obtained by our group and other laboratories revealed that this mRNA is detectible in most tumor and non-tumor cell lines, but its levels are the lowest among all polyamine-metabolizing enzymes and regulatory proteins." (PMID 38994986, 2024).
cancer (5 papers, 2017 to 2025). A tumor composed of atypical neoplastic, often pleomorphic cells that invade other tissues. "Yet this assumption has never been verified; we previously reported that GBM cell lines differ from other cancer cell lines by the pronounced expression of PAOX, one of the polyamine-catabolizing enzymes." (PMID 40806477, 2025). "PAOX overexpression correlates with the resistance of cancer cells to genotoxic antitumor drugs, indicating that PAOX may be a useful therapeutic target." (PMID 38994986, 2024). "No significant changes were noted in polyamine oxidase (PAOX) and spermine oxidase (SMOX) expression between normal and cancer." (PMID 29240775, 2017). "Our data correlate with the absence of PAOX activity in colon and breast cancer cell lines reported by R. Casero’s group, in HEK293T cells shown by K. Porter’s group, as well as with very weak staining of retinal glial cells with anti-PAOX antibodies." (PMID 38994986, 2024).
infection (4 papers, 2013 to 2022). The state of being infected such as from the introduction of a foreign agent such as serum, vaccine, antigenic substance or organism. "In this study, a weak increase of diamine- and polyamine-oxidase activities was recorded in stressed berries, but declined after pathogen infection." (PMID 30050554, 2018). "A weak increase of diamine- and polyamine-oxidase activities was also recorded in stressed berries, but declined after pathogen infection." (PMID 30050554, 2018). "In tobacco, polyamine oxidase (PAO) protein and the specific PAO enzymatic activities increased after infection with compatible plant-pathogenic bacterium Pseudomonas syringae pv tabaci." (PMID 23509803, 2013). "The level of polyamine oxidase expression was reduced in the flax seedlings infected with F. oxysporum, indicating a lack of involvement in the lignification process by polyamine at this stage of infection in this manner." (PMID 25972886, 2015). "The analysis of the fibroblasts revealed that the PAOX expression significantly increased the MMP-1 secretion compared with that of the infection with the control virus and mock infection, but it did not significantly affect the type I collagen secretion." (PMID 36142401, 2022).
retinopathy (1 paper, 2018). "We have previously shown that inhibition of polyamine oxidase (PAO) using MDL 72527 significantly reduced retinal neurodegeneration and cell death signaling pathways in hyperoxia-mediated retinopathy." (PMID 30686964, 2018).
PAOX also shares sentences with these, for which no sentence is quoted: brain infarction (1 paper); cervical cancer (1); chronic myeloid leukemia (1); colorectal cancer (1); endometrial cancer (1); fungal infection (1); hepatoma (1); lung adenocarcinoma (1); microcephaly (1); neuroblastoma (1); osteosarcoma (1); prostate carcinoma (1); renal cell carcinoma (1).